KIF20A (kinesin family member 20A)
Diseases named in the same sentence as KIF20A in open-access papers (continued):
Sharing a sentence is not in itself a finding about the gene and the disease.
renal carcinoma (6 papers, 2020 to 2025). A carcinoma arising from the epithelium of the renal parenchyma or the renal pelvis. "Overexpression of KIF20A has been associated with aggressive behavior and poor prognosis in renal cancer patients." (PMID 37310408, 2023). "In addition, up-regulated KIF20A expression in renal carcinoma tissues and its association with prognosis were also predicted." (PMID 33941190, 2021). "Studies have shown that KIF20A is overexpressed in renal cancer cells compared to normal kidney cells." (PMID 37310408, 2023). "Through GEPIA, HAP and other databases, we found that the expression of IRF6 and KIF20A in ccRCC is likely to be correlated with the pathological stage and overall survival rate of renal carcinoma patients." (PMID 33941190, 2021). "Secondly, subsequent studies are still needed to properly dissect the mechanism by which KIF20A promotes the progression of renal cancer." (PMID 33232285, 2020). "Increased levels of KIF20A expression were also observed in renal cancer, according to TCGA, ICGC and GSE (GSE40435, GSE36895, GSE46699 and GSE53757) databases (P<0.001)." (PMID 33232285, 2020). "Similarly, suppression of KIF20A has been shown to inhibit invasion and infiltration in renal cancer." (PMID 41013841, 2025). "Overall, the relationship between KIF20A and renal cancer suggests that KIF20A may play a critical role in development, and targeting KIF20A may be a potential strategy for the treatment of renal cancer." (PMID 37310408, 2023). "Likewise, MTT assay result indicated that KIF20A knockdown is able to inhibit the proliferation of renal cancer cells." (PMID 33232285, 2020). "In this work, we were able to confirme that KIF20A is overexpressed in renal cancer tissue and could also promote the proliferation and metastasis of related tumor cells." (PMID 33232285, 2020). "Upon performing a series of in vitro experiments, we found that KIF20A is up-regulated in ccRCC tissue, and could promote the proliferation and invasion of renal cancer cells." (PMID 33232285, 2020). "KIF20A may be involved in the progression of various types of cancer, including renal cancer." (PMID 37310408, 2023). "In addition, inhibiting KIF20A expression has been shown to reduce renal cancer cell proliferation and to induce cell death, suggesting that KIF20A may be a potential therapeutic target for renal cancer." (PMID 37310408, 2023). "ChIP experiment verified the combination of IRF6 and KIF20A promoters, indicating that KIF20A was a target of IRF6 in renal carcinoma." (PMID 36798768, 2023). "Interestingly, KIF20A could partially reverse the effects of IRF6 on renal carcinoma cells." (PMID 36798768, 2023). "However, unlike most cancer types which exhibited elevated KIF20A expression that remained relatively constant across tumor stages, renal carcinomas displayed a more gradual increase that continued with increasing disease severity." (PMID 33819271, 2021).
head-and-neck malignant tumors (5 papers, 2016 to 2024). "Significant KIF20A-specific T-helper type 1 (TH1) cell responses were detected in patients with malignant head-and-neck cancer receiving this immunotherapy (8/16, 50%)." (PMID 28081138, 2017). "Indeed, KIF20A-specific Type 1 helper T cell responses have been identified in head and neck malignant tumor patients." (PMID 27941992, 2016).
soft tissue sarcoma (5 papers, 2020 to 2025). A malignant neoplasm arising from muscle tissue, adipose tissue, blood vessels, fibrous tissue, or other supportive tissues excluding the bones. "A previous study reported that the knockdown of KIF20A suppressed tumor growth in soft tissue sarcoma, both in vitro and in vivo." (PMID 40600015, 2025). "KIF20A served as a pivotal hub gene within the biological regulatory network of soft tissue sarcoma (STS) and was significantly correlated with the prognosis of patients." (PMID 40600015, 2025). "In soft tissue sarcoma, KIF20A gene knockout can inhibit the proliferation, migration and invasion of soft tissue sarcoma cells, promote cell apoptosis, and inhibit tumor growth." (PMID 33941190, 2021).
COVID-19 (4 papers, 2022 to 2025). A disease caused by infection with severe acute respiratory syndrome coronavirus 2. "The GSE167028 and GSE150392 datasets were subjected to a recent bioinformatic analysis, which unveiled six critical genes (CDK1, KIF20A, PBK, KIF2C, CDC20, and UBE2C) associated with COVID-19 myocarditis." (PMID 40230577, 2025). "In addition, CAV1, CDC20, and KIF20A were also identified as hub genes in COVID-19 by other researchers." (PMID 35957855, 2022). "Among the ten candidate hub genes, we found that 8 hub genes were differentially upregulated in HBV and COVID-19, so we further narrowed the scope of the study to 8 hub genes, including CDK1, E2F7, E2F8, TYMS, KIF20A, CENPE, TPX2, HMMR." (PMID 40408617, 2025). "Based on 5 algorithms of the CytoHubba plug-in, six genes (CDK1, KIF20A, PBK, KIF2C, CDC20, UBE2C) were confirmed as critical genes related to COVID-19 Myocarditis." (PMID 35749386, 2022). "Eventually, 6 genes (CDK1, KIF20A, PBK, KIF2C, CDC20, UBE2C) were identified by CytoHubba plug-in of Cytoscape as critical genes of COVID-19 Myocarditis for future study." (PMID 35749386, 2022). "Based on topological algorithms (i.e., degree), in this study, CDK1, KIF20A, PBK, KIF2C, CDC20, and UBE2C were identified as critical genes that may be potential biomarkers for COVID-19 Myocarditis." (PMID 35749386, 2022). "It is worth highlighting that critical genes (CDK1, KIF20A, PBK, KIF2C, CDC20, UBE2C) may be potential biomarkers and treatment targets of COVID-19 Myocarditis for future study." (PMID 35749386, 2022).
glioblastoma (4 papers, 2013 to 2024). The most malignant astrocytic tumor (WHO grade IV). "We further focused on KIF11 and KIF20A expression in glioblastoma and found general over-expression in this pathology in two additional studies." (PMID 24327603, 2013). "KIF20A transcripts were found mostly in ECs in glioblastoma (n=4 patients, arrows), matching the vascular localization of CD31." (PMID 24327603, 2013). "For grade 4 glioblastoma brain cancer, CCNB1 was indicated as a part of hub genes (with CDC6, KIF23, and KIF20A) and its expression correlated with prognosis, suggesting it as a potential biomarker for diagnosis and as a target for treatment." (PMID 39409884, 2024). "Mklp2/KIF20A protein showed an even stronger expression in endothelial cells in several normal tissues (heart, placenta, endometrium, oral mucosa) and glioblastoma vessels." (PMID 24327603, 2013).
nasopharyngeal carcinoma (4 papers, 2017 to 2025). A carcinoma arising from the nasopharyngeal epithelium. "However, the clinical value of KIF20A in nasopharyngeal carcinoma (NPC) is unknown." (PMID 28081138, 2017).
ovarian clear cell cancer (4 papers, 2019 to 2023). An invasive malignant neoplasm that arises from the ovary and is characterized by a predominance of clear and hobnail malignant epithelial cells. "As it was further shown that KIF20a knockout inhibits tumor proliferation in ovarian clear cell carcinoma, we concluded that KIF20A is a tumorbiological marker, associated with unfavorable prognosis." (PMID 36768616, 2023). "In ovarian clear-cell carcinoma cells, KIF20A may significantly promote the proliferation of ovarian clear-cell carcinoma cells." (PMID 33952272, 2021).
Autoimmunity (3 papers, 2011 to 2023). The occurrence of an immune reaction against the organism's own cells or tissues. "Moreover, KIF20A peptides were shown to cause expansion of HLA-A2-restricted cytotoxic T cells in HLA-A2 transgenic mice without causing autoimmunity, and those T cells successfully exhibited cytotoxic responses to cancer cells expressing KIF20A." (PMID 27941992, 2016). "No pathological change that suggests autoimmunity, such as lymphocyte infiltration or tissue destruction, was observed, indicating that lymphocytes stimulated with the KIF20A-8 peptide were safe at least in HLA-A2 Tgm." (PMID 21179034, 2011). "HLA-A2 transgenic mice (Tgm) were used to identified KIF20A-derived and HLA-A2-restricted mouse CTL epitopes, KIF20A-2, KIF20A-8 and KIF20A-28 could induce HLA-A2-restricted CTLs in HLA-A2 Tgm without autoimmunity." (PMID 36798768, 2023).
esophageal squamous cell carcinoma (3 papers, 2020 to 2025). Esophageal squamous cell carcinoma (ESCC) is a type of esophageal carcinoma (EC) that can affect any part of the esophagus, but is usually located in the upper or middle third. "KIF20A and RAD51AP1 were more informative biomarkers of esophageal squamous cell carcinoma." (PMID 32963620, 2020).
Ewing sarcoma (3 papers, 2015 to 2021). A small round cell tumor that lacks morphologic, immunohistochemical, and electron microscopic evidence of neuroectodermal differentiation.
fibrosarcoma (3 papers, 2024 to 2025). A malignant mesenchymal fibroblastic neoplasm affecting the soft tissue and bone. "It had been reported that the expression of KIF20A was significantly elevated in several malignancies, including lung adenocarcinoma, non-small cell lung cancer, prostate cancer, fibrosarcoma, and colorectal cancer." (PMID 40600015, 2025). "Recent discoveries suggested that the promotion of fibrosarcoma progression, which is mediated by KIF20A, heavily relied on the critical involvement of the PI3K-Akt signaling pathway." (PMID 41462522, 2025). "KIF20A promotes the progression of castration-resistant prostate cancer by activating androgen receptor signaling and promotes the progression of fibrosarcoma via the PI3K-Akt signaling pathway." (PMID 39902297, 2024). "Consequently, targeting KIF20A could be a potential therapeutic strategy for fibrosarcoma treatment." (PMID 41462522, 2025).
head and neck squamous cell carcinoma (3 papers, 2017 to 2026). A squamous cell carcinoma that arises from any of the following anatomic sites: lip and oral cavity, nasal cavity, paranasal sinuses, pharynx, larynx, and salivary glands. "Analysis of publically-available microarray data (GSE12452, GSE13597, GSE53819, and TCGA data for Head and Neck Squamous Cell Carcinoma (HNSCC)) revealed KIF20A was upregulated in NPC tumor samples and HNSCC compared with normal tissues." (PMID 28081138, 2017).
leukemia (3 papers, 2022 to 2024). A malignant (clonal) hematologic disorder, involving hematopoietic stem cells and characterized by the presence of primitive or atypical myeloid or lymphoid cells in the bone marrow and the blood. "Since immature hematopoietic cells have proved to express KIF20A highly, there has been enormous research to find KIF20A to treat leukemia." (PMID 37231064, 2023).
medulloblastoma (3 papers, 2021 to 2024). A malignant, invasive embryonal neoplasm arising from the cerebellum. "The expression levels of AURKA and KIF20A were discovered to be linked with the prognosis of medulloblastoma patients." (PMID 35574421, 2022). "Here, we test this idea by targeting KIF20A, a mitotic kinesin crucial for the control of cell division modes, in a genetic model of medulloblastoma (MB) and human MB cells." (PMID 33976373, 2021). "They show that Kif20a depletion suppresses tumour formation in genetic and xenograft mouse models of medulloblastoma, indicating the value of targeting daughter cell fate specification." (PMID 33976373, 2021). "In conclusion, This study found that aurora kinase A (AURKA) and kinesin family member 20A (KIF20A) may be involved in the initiation and development of medulloblastoma, have a close association with prognosis, and may become a potential therapeutic target and prognostic marker of MED." (PMID 35574421, 2022).
osteosarcoma (3 papers, 2015 to 2023). A usually aggressive malignant bone-forming mesenchymal neoplasm, predominantly affecting adolescents and young adults. "Across all Ewing and osteosarcoma cell lines eleven genes were found to be either significantly (P < 0.05, Bonferroni correction) repressed (KIF20A, IDH1, SCD, GPSM2, EIF2AK4, HIBCH) or induced (STK19, DNAJC24, MTG2, FAM175B, CYB5D1) following non DNA-damaging XI-006 treatment (0.5 μM)." (PMID 26095524, 2015). "Eight out of the 54 hub‐genes (ASPM, CENPF, KIF14, KIF20A, RCC1, SMC2, SRC, and TOP2A) were significantly decreased after NACT (criteria: |fold change| ≥ 2 and adjusted p value < 0.05), consistent with the central role of these hub genes in osteosarcoma." (PMID 37457661, 2023).
pancreatic ductal adenocarcinoma (3 papers, 2016 to 2025). An infiltrating adenocarcinoma that arises from the epithelial cells of the pancreas. "As the proliferation and migration of pancreatic ductal adenocarcinoma cells were significantly reduced by silencing KIF20A, KIF20A has been suggested as a novel anti-cancer drug target." (PMID 27941992, 2016).
renal cell carcinoma (3 papers, 2020 to 2023). "For renal cell carcinoma, KIF20A was regarded as promoting proliferation, invasion and migration of ccRCC, our study proved the carcinogenic property in sPRCC2 from our cohort." (PMID 36927438, 2023). "Coincidentally, higher levels of KIF20A protein was also observed in renal cell carcinoma cell lines (OSRC-2, SW839, Caki-1 and A498), where A498 and Caki-1 presented the highest protein levels." (PMID 33232285, 2020).
sarcoma (3 papers, 2015 to 2025). A usually aggressive malignant neoplasm of the soft tissue or bone. "A multiple peptide cocktail vaccine (KOC1, FOXM1 and KIF20A) has already been tested in patients with refractory pediatric sarcoma in a phase I study." (PMID 26640950, 2015). "Patients exhibiting high KIF20A expression in sarcomas demonstrated reduced OS and DFS durations." (PMID 40600015, 2025). "The GEPIA website revealed that the mRNA levels of KIF20A were aberrantly upregulated in sarcomas." (PMID 40600015, 2025). "Furthermore, multiple peptides cocktail vaccine (KOC1, FOXM1 and KIF20A) has already been tested for the patients with refractory pediatric sarcoma in phase I study." (PMID 26640950, 2015). "The GEPIA website indicated a positive correlation between KIF20A and DEPDC1 expression in sarcoma." (PMID 40600015, 2025).
brain tumor (2 papers, 2021 to 2024). "In this report, our genetic analyses of KIF20A in both normal and cancer-initiating cerebellar GNPs presents an experimental validation of a cell division mode regulator as a potential target for brain tumor inhibition." (PMID 33976373, 2021). "KIF20A, a mitotic kinesin, plays an important role in controlling the mode of division of neural progenitor cells (NPC) in both normal brain cells and brain tumor cells, and KIF20A knockdown induces a transition from proliferative to differentiative divisions in NPC." (PMID 38449858, 2024). "Based on these observations, we anticipate that disruption of KIF20A function in brain tumor-initiating cells would similarly promote the affected cells to leave the cell cycle and become post mitotic, and as a result, this should lead to inhibition of brain tumor initiation and/or progression." (PMID 33976373, 2021). "To address whether KIF20A might be similarly crucial for maintaining the proliferation of brain tumor-initiating cells, we crossed the Kif20afl/fl floxed mice with Atoh1-CreER; Ptcfl/fl mice to generate a strain of compound mice carrying the Atoh1-CreER; Ptcfl/fl; Kif20afl/fl alleles." (PMID 33976373, 2021). "Our results revealed that, in comparison to the control group, the group of mice that received treatment showed significantly slower growth of brain tumors and better overall survival, indicating that inhibition of KIF20A expression could suppress cell proliferation in a growing tumor." (PMID 33976373, 2021).
cardiomyopathy (2 papers, 2018 to 2022). A disease of the heart muscle or myocardium proper. "In one case report, exome sequencing analysis of children with congenital cardiomyopathy identified the KIF20A complex and in subsequent in vitro experiments in zebrafish, KIF20A was identified as the phenotypic gene for cardiomyopathy." (PMID 35749386, 2022). "In a zebrafish model we showed that translational blocking of the zebrafish kif20a gene resulted in a cardiomyopathy phenotype and that kif20a is required for proper function, suggesting KIF20A has an evolutionary conserved function in heart development." (PMID 29357359, 2018). "Translational blocking of KIF20A in a zebrafish model resulted in a cardiomyopathy phenotype." (PMID 29357359, 2018).
colon cancer (2 papers, 2019 to 2022). "In most tumors, upregulation of KIF20A suggests a poor prognosis of patients, except for colon cancer, where it has been found that the AURKA upregulation in colon cancer suggests better prognosis of patients with colon cancer." (PMID 35574421, 2022). "At the same time, KIF20A expression was analyzed in a series of colon cancer cases from the TCGA database between colon, rectum, and different types of tumors." (PMID 31841120, 2019).
liposarcoma (2 papers, 2022 to 2025). A usually painless malignant tumor that arises from adipose tissue. "While KIF20A has been implicated in promoting tumorigenesis in other cancers, its specific involvement in liposarcoma requires further investigation." (PMID 40600015, 2025). "Here, our findings revealed that the expression levels of DEPDC1 and KIF20A were elevated in liposarcoma compared to the paired adjacent adipose tissues, with their expression positively correlating with the malignancy of liposarcoma." (PMID 40600015, 2025). "The effect of si-KIF20A antagonized the activating influence of DEPDC1 overexpression on AKT/PI3K/mTOR in liposarcoma cells." (PMID 40600015, 2025). "In our study, differential expression analysis and hub gene identification revealed that KIF20A was differentially expressed between liposarcoma and normal tissues." (PMID 40600015, 2025). "We measured the expression levels of DEPDC1 and KIF20A in clinical liposarcoma tissues at mRNA and protein levels." (PMID 40600015, 2025). "In brief, these results indicated that DEPDC1 facilitated malignant phenotypes by modulating KIF20A in liposarcoma cells." (PMID 40600015, 2025). "The qPCR results revealed that the KIF20A mRNA level in liposarcoma tissues was significantly higher than in normal adipose tissues from the same patients with liposarcoma (n = 26), as determined by a paired t-test." (PMID 40600015, 2025). "The deletion of KIF20A partially mitigated the promoting effect of DEPDC1 on the malignant phenotype of liposarcoma cells and the activation of PI3K/AKT/mTOR signaling pathway." (PMID 40600015, 2025). "Nevertheless, the precise role and potential mechanisms by which KIF20A influenced the growth and metastasis of liposarcoma remained elusive." (PMID 40600015, 2025). "Future research is needed to determine whether KIF20A plays a similar role in liposarcoma, particularly in processes like cell proliferation, migration, and invasion." (PMID 40600015, 2025). "The upregulation of DEPDC1 promoted the proliferation, invasion, and migration of liposarcoma cells, which could be reversed by downregulating KIF20A." (PMID 40600015, 2025). "In conclusion, this study suggested that DEPDC1 might interact with KIF20A to promote the occurrence and progression of liposarcoma by activating PI3K/AKT/mTOR signaling pathway." (PMID 40600015, 2025). "In conclusion, the expression of DEPDC1 and KIF20A was elevated in liposarcoma." (PMID 40600015, 2025). "Moreover, the overexpression of DEPDC1, coupled with the simultaneous knockdown of KIF20A in liposarcoma cells, partially inhibited the progression in malignant phenotypes of these cells and the activation of PI3K/AKT/mTOR signaling pathway compared to the control groups." (PMID 40600015, 2025). "Indeed, the role of KIF20A in liposarcoma remains unexplored in the current scientific literature." (PMID 40600015, 2025).